BCAT1 (branched chain amino acid transaminase 1)
Diseases named in the same sentence as BCAT1 in open-access papers (continued):
Sharing a sentence is not in itself a finding about the gene and the disease.
cancer (continued). "The TGF-β/SMAD5 axis directly upregulates the BCAT1 activity of CAFs to allow CAFs to produce more BCKAs, which can be absorbed by cancer cells directly." (PMID 36115986, 2022). "The close positive relevance of BCAT1 expression to several immune scores was also detected in pan‐cancer analyses." (PMID 34984849, 2022). "In cancers with statistically significant results (p < 0.05), downregulated BCAT1 expression was detected in elderly patients (except for ESCA) and males (except for SARC)." (PMID 34984849, 2022). "The differential expression of BCAT1 was detected in various cancers (p < 0.05), which is relevant to some DNA methyltransferases expression." (PMID 34984849, 2022). "It was well known that cancer cells undergo metabolic reprogramming under epigenetic regulation, and BCAT1 enhances drug resistance mechanisms by mediating metabolic reprogramming of drug resistance mechanisms." (PMID 36119495, 2022). "We found knockdown of BCAT1 significantly reduced the activities of Ras/BRaf/MEK/ERK signalling kinases in SCLC cells, indicating this pathway is involved in BCAT1‐mediated cancer cell proliferation." (PMID 35318805, 2022). "For the first time, the research comprehensively demonstrates the overexpression of BCAT1 in pan‐cancer, which improves the understanding of the pathogenesis of BCAT1 in pan‐cancer." (PMID 34984849, 2022). "HNSCC, LUSC, and READ were the three cancers (HNSCC was the top one) with the most conspicuous correlations between BCAT1 expression and infiltration levels of all six immune cells, particularly for dendritic and neutrophilic cells." (PMID 34984849, 2022). "Overall, the research highlights an essential role of BCAT1 expression in pan‐cancer, providing a novel and potential therapeutic target for various cancers." (PMID 34984849, 2022). "The study comprehensively analyzes the expression, potential mechanisms, and clinical significance of BCAT1 in pan‐cancer through utilizing 16,847 samples, providing novel clues for the treatment of cancers." (PMID 34984849, 2022). "Upregulated BCAT1 expression represented a poor prognosis for cancers patients, and it serves as a potential marker for cancer immunotherapy." (PMID 34984849, 2022). "For the first time, this study comprehensively demonstrates a high expression of BCAT1 in pan‐cancer, which improves the understanding of the pathogenesis of BCAT1 in pan‐cancer." (PMID 34984849, 2022). "The expression of BCAT1 was diverse in various normal tissues, and the same phenomenon was observed in the cell lines of 14 cancers." (PMID 34984849, 2022). "Emerging evidence suggests that BCAT1 plays a vital role in the progression of many cancers, especially highlighting the tight connection between BCAT1 level and IDH1 mutation status." (PMID 33493139, 2021). "BCAT1 expression commonly correlates with aggressive cancer growth and progression and has attracted substantial scientific attention in the past few years." (PMID 33790982, 2021). "Our results confirmed that BCAT1 enhances the mTOR-mediated autophagy via BACC Leu metabolism in cancer cells, which finally leads to a reduced cisplatin sensitivity." (PMID 33568627, 2021). "Our results showed that the cisplatin-induced the upregulation of BCAT1, which decreased the cisplatin sensitivity of cancer cells by facilitating autophagy via the Leu-mediated activation of the mTOR signaling pathway." (PMID 33568627, 2021). "In this study, we revealed that cisplatin triggered autophagy in cancer cells, with an increase in BCAT1 expression." (PMID 33568627, 2021). "BCAT1 regulates mTOR-mediated autophagy via branched-chain amino acid metabolism, thus reducing the sensitivity of cancer cells to cisplatin." (PMID 34976806, 2021). "Although the role of BCKDH complex and BCAT isoforms (cytosolic BCAT1 or mitochondrial BCAT2) have been widely explored in different cancers, the role of BCKDK remains mostly elusive." (PMID 34526485, 2021).
cancer (continued). "Loss of BCKDK led to reduced expression of BCAT1 and HIBCH, candidate genes augmented in several cancers." (PMID 34526485, 2021). "Increased levels of BCAT1, a target of c-MYC, has been previously associated with more aggressive cancers." (PMID 32907612, 2020). "BCAT1 has been shown overexpression in some human malignancies, which is highly correlated with initiation and progression of malignant tumor." (PMID 31226958, 2019). "Based on online literature search, we found that OLR1, GPNMB, PRRX1 and BCAT1 promote cancer migration and invasion in various types of cancer." (PMID 29851214, 2018). "Detectable methylation in one or both genes was present in 98.9% (90/91) of cancer tissue, with methylated BCAT1 present in 89/91 (97.8%) and methylated IKZF1 present in 79/91 (86.8%)." (PMID 29796114, 2018). "The cytosolic branched chain-amino transferase 1 (BCAT1), which converts BCAAs to their corresponding branched-chain a-keto acids is involved in cancer proliferation and has been proposed as a prognostic cancer marker." (PMID 30096165, 2018). "Multiple DEGs, including FEN1, BCAT1, AGPS and CCL3, have been implicated in the progression of various cancers." (PMID 29033691, 2017). "The BCAT1 methylation assay was positive in 53 of the 218 analysed specimens including 48 (65%) cancers and 5 (4%) controls." (PMID 25928810, 2015). "A total of 41/74 cancer cases were positive for both methylated BCAT1 and IKZF1 DNA compared to only 1/144 control)." (PMID 25928810, 2015). "For a specimen containing approximately 5 % methylated BCAT1 and IKZF1 DNA the models estimate a relative risk of 5 for having early stage cancer." (PMID 26445409, 2015). "A two-gene classifier model (“either or” rule) improved segregation of CRC from controls, with 57 of 74 cancers (77%) compared to only 11 of 144 (7.6%) controls being positive for BCAT1 and/or IKZF1 DNA methylation." (PMID 25928810, 2015). "The relationship between measured levels of circulating methylated BCAT1 or IKZF1 DNA in plasma and cancer stage was modeled to estimate the likelihood of cancer, given a methylated BCAT1 or IKZF1 DNA mass estimate per triplicate assay." (PMID 25928810, 2015). "Of the 129 cancer cases, 57 % were methylation positive for BCAT1 and 48 % for IKZF1, with 66 % methylation positive by either gene." (PMID 26445409, 2015). "For those with cancer, 51/129 (40 %) were concordant and 34/129 discordant (26 %), with BCAT1 detecting most of the discordant cases (23/34, 68 %) (McNemar’s, p = 0.06)." (PMID 26445409, 2015). "This selective inhibition makes it suitable for testing in cancers with BCAT1 overexpression." (PMID 40507232, 2025). "BCAT1 catalyzes the initial step of branched-chain amino acid catabolism and is known to promote cancer proliferation and invasion through the activation of either the phosphatidylinositol 3-kinase/protein kinase B/mammalian target of rapamycin pathway or Wnt/β-catenin signal transduction." (PMID 40242470, 2025). "Solid evidence from various cancers has demonstrated BCAT1’s direct regulation in the mTOR pathway." (PMID 40438606, 2025). "Their findings suggest that G. lucidum may affect important metabolic pathways associated with cancer progression by targeting G6PD and BCAT1." (PMID 41462671, 2025). "This suggests that GABA analogs like gabapentin may not only inhibit BCAT1 directly but also potentially enhance the effects of TKIs, providing a promising therapeutic approach for targeting BCAT1 in cancer." (PMID 40507232, 2025). "GABA derivatives are an important chemical class of BCAT1 inhibitors, and therefore, the findings in the present study represent great progress both in the discovery of potent BCAT1 inhibitors with new chemical structures and in the treatment of cancer resistance." (PMID 40005214, 2025). "BCAT1 is known to support cancer cell growth in a glioblastoma model." (PMID 39795113, 2024). "The immune system became more active in BCAT1 mutant cancers." (PMID 39324007, 2024).
cancer (continued). "Although further research is needed to determine whether BCAT1/2 catabolizes or synthesizes BCAAs in cancer cells, BCAT1/2 could be a potential therapeutical target for cancer treatment." (PMID 39795113, 2024). "The increased expression of BCAT1 in various malignant tumors has been verified." (PMID 37298317, 2023). "Although BCAT1 catalyzes transamination in both directions and the breakdown of BCAAs is the predominant reaction in most cell types, BCAT1 generates BCAAs via the reverse reaction in cancer metabolic reprogramming." (PMID 37076565, 2023). "To further delineate the upstream targets of BCAT1, we evaluated several potential signaling pathways downregulated in P2x1-null LICs, such as transcriptional misregulation in cancer, and we found that the Pbx3 mRNA level in P2x1-null LICs was significantly decreased to 10% of that in WT LICs." (PMID 36418376, 2023). "Moreover, BCAT1 and its metabolites participate in the metabolism of cancer cells through different mechanisms." (PMID 37704698, 2023). "In the following years, BCAT1 was gradually identified as an important prognostic cancer marker." (PMID 36998464, 2023). "BCAT1 expression also demonstrated conspicuous ability to distinguish some cancers tissues from their normal tissues (AUC > 0.7), indicating its potential to detect cancers." (PMID 34984849, 2022). "The associations of BCAT1 expression with its mutations were found in some cancers, and dysregulated MMR genes may take part in BCAT1 mutations." (PMID 34984849, 2022). "In addition, SOX2 regulates the epithelial-mesenchymal transition (EMT) of various cancer types through Wnt signaling, and it has been reported that BCAT1 can induce the EMT process in LC cells." (PMID 36119495, 2022). "Furthermore, the high BCAT1 expression represents shorter DSST for patients with the eight cancers (ACC, etc.)and SKCM, clearly suggesting its risk roles in these cancers." (PMID 34984849, 2022). "BCAT1 expression showed conspicuous clinical significance in cancers." (PMID 34984849, 2022). "Furthermore, compared to corresponding normal tissues, BCAT1 was differentially expressed in multiple cancer tissues based on TCGA data." (PMID 34984849, 2022). "In addition, further in vivo and in vitro experiments should be undertaken to investigate the mechanisms of BCAT1 in pan‐cancer." (PMID 34984849, 2022). "However, BCAT1 was overexpressed in most cancers such as GC and BC and was involved in various regulatory mechanisms." (PMID 36119495, 2022). "Collectively, BCAT1 expression was possibly a marker for prognosis and identifying cancers." (PMID 34984849, 2022). "In addition, one study reported that curcumin reduced α-KG levels by inhibiting BCAT1 expression and the mTOR pathway, and finally induced apoptosis in cytarabine-resistant ML cancer cells." (PMID 36119495, 2022). "Moreover, the study revealed the significance of BCAT1 expression in differentiating some cancers (e.g., CHOL) from their control tissues, and such a finding has not before been reported." (PMID 34984849, 2022). "In addition, the changes in BCAT1 levels are statistically different in different tumors, and its overexpression in pan-cancer has very obvious prognostic significance." (PMID 36119495, 2022). "Cytosolic branched-chain aminotransferase 1 (BCAT1) and mitochondrial branched-chain aminotransferase 2 (BCAT2), metabolic enzymes of BCAA, appear to vary between cancer types, but BCAT1′d expression is correlated with increased aggression of growth and progression." (PMID 35054779, 2022). "Also, the knockdown of BCAT1 or the administration of leucine activated mTOR signaling, inhibited autophagy, and increased cisplatin sensitivity in cancer cells in vivo." (PMID 33568627, 2021). "Notably, changes in BCAAs metabolism in different cancers are largely due to the overexpression of BCAT1." (PMID 34445444, 2021).
cancer (continued). "To determine whether BCAT1 modulates metastasis in vivo, we intracardially inoculated cancer cells stably expressing either shBCAT1 or control shRNA into nude mice, and examined metastasis using bioluminescence imaging." (PMID 34646394, 2021). "Flow cytometry analysis showed that CD133, a cancer cell stemness marker 38, was expressed in a higher proportion of L2 and L6 cells expressing scrambled BCAT1 shRNA, and that knockdown of BCAT1 expression significantly reduced the proportion of CD133-positive cells." (PMID 34646394, 2021). "In addition, branched-chain amino acids or leucine treatment inhibited cisplatin- or BCAT1-mediated autophagy and increased cisplatin sensitivity by activating mTOR signaling in cancer cells." (PMID 33568627, 2021). "BCAT1 has been proven to be involved in the progression of cancer." (PMID 32855634, 2020). "All these studies suggest an important role of BCAT1 as a potential prognostic cancer marker." (PMID 32238881, 2020). "In another way, cancer-associated fibroblasts (CAFs) present an up-regulated BCAAs catabolism and are able to fuel PDAC cells with branched-chain α-ketoacid (BCKA), thanks to their elevated BCAT1 (Branched chain amino acid transaminase 1) activity." (PMID 33371431, 2020). "Or does BCAT1 affects the activity of BCKDK in cancer development?" (PMID 32238881, 2020). "As DNMT1 plays an important role in mediating the methylation of microRNAs in cancer cells, we investigated whether it was involved in the regulation of hsa-miR-124-3p / BCAT1 in ESCC." (PMID 31226958, 2019). "The cytosolic branched-chain aminotransferase 1 (BCAT1), a BCAAs metabolic enzyme, has emerged as an important prognostic cancer marker, and metabolism of BCAAs also has a potential as target therapies for development of new cancer." (PMID 29570613, 2018). "Our own dataset only included four Stage I cancers, and while two (50%) of these were detected, the sample numbers are presently too low to conclude whether the methylated BCAT1/IKZF1 test will give good detection of Stage I cancers." (PMID 25928810, 2015). "Thus the likelihood of a plasma specimen with ≥ 20 pg methylated BCAT1 or IKZF1 DNA to be an early stage cancer is approximately 9:1 and 210:1, respectively (early stage CRC: control)." (PMID 25928810, 2015). "Next, we decided to verify if short-hairpin RNA (shRNA)-mediated BCAT1 gene knockdown could produce any cancer-related phenotypic changes in EOC cells." (PMID 26372729, 2015). "BCAT1 may drive the ammonification of BCAA in the circulation, causing these cancer cells to accumulate BCAA, bind to Sestrin2, activate the mTORC1 signaling pathway, phosphorylate downstream effector molecules, and regulate important cellular biological processes." (PMID 39324007, 2024). "However, more work must be carried out, focusing particularly on the relation of BCAT1 with its mutations and MMR; doing so may contribute to the understanding of dysregulated BCAT1 expression in pan‐cancer." (PMID 34984849, 2022). "Therefore, we propose that BCAT1 may interact and regulate multiple cellular signalling pathways to exert its functions, which are most likely cancer type‐specific." (PMID 35318805, 2022). "In addition, BCAT1 was also involved in the mitochondrial synthesis of cancer cells." (PMID 36119495, 2022). "BCAT1 may have the potential as a therapeutic target for cancers." (PMID 34984849, 2022). "However, the molecular mechanism of how BCAT1 regulates cisplatin chemosensitivity in cancer cells remains unclear." (PMID 33568627, 2021). "Thus, BCAT1/2 inhibition is a promising therapeutic target in a subset of cancers." (PMID 34203535, 2021). "In these diseases, BCAT1 could represent an important prognostic cancer marker." (PMID 34445444, 2021). "The role of BCAT1 in other cancers may also be investigated." (PMID 28245795, 2017).
cancer (continued). "Branched-chain amino acid transaminases (BCATs), including BCAT1 and BCAT2, play pivotal roles in tumorigenesis and therapeutic resistance in various cancers." (PMID 41716286, 2026). "BCAT1, along with bone marrow stromal antigen 2 (BST 2) and the tyrosine kinase MERTK, promotes cancer progression by regulating TAM 2 polarization, offering a potential target for pancreatic cancer treatment." (PMID 40438606, 2025). "BCAT1, a pivotal enzyme in BCAA metabolism, has emerged as a focal point in cancer research due to its diverse roles across various malignancies." (PMID 39075053, 2024). "Methylation of branched chain amino acid transaminase 1 (BCAT1) and IKZF1 has been recurrently observed in CRC, with nearly all cancer tissues displaying significant methylation levels of these two genes." (PMID 38464391, 2024). "‘Metabolic pathways’ include UDP-glucose 6-dehydrogenase (UGDH), tripartite motif containing 44 (TRIM44), and branched-chain amino acid transaminase 1 (BCAT1), and these genes are known to affect cancer development." (PMID 37667226, 2023). "TGF-β secreted by cancer cells upregulates BCAT1 activity by activating SMAD5 in CAFs, thereby increasing the secretion of BCKAs, which are supplied to cancer cells for BCAA synthesis." (PMID 37033960, 2023). "BCAT1 and BCKDK regulate the BCAA metabolism and cancer progression and have been identified as a marker for cancer prognosis." (PMID 37460470, 2023). "For example, BCAT1 expression was dramatically and positively related to infiltration levels of neutrophil, dendritic cells, CD4 T cells, and CD8 T cells in some cancers (e.g., HNSCC)." (PMID 34984849, 2022). "In our research, BCAT1 expression was correlated with the three DNA methyltransferase genes––DNMT1, DNMT3A, and DNMT3B in some cancers." (PMID 34984849, 2022). "In our study, BCAT1 expression was found to be related to MSI, TMB, and immune checkpoint genes in several cancers (e.g., COAD and SARC)." (PMID 34984849, 2022). "Significant correlations of BCAT1 expression with the three methyltransferases—DNMT1, DNMT3A, and DNMT3B—were detected in some cancers." (PMID 34984849, 2022). "In three cancers––COAD, READ, and HNSCC, BCAT1 expression showed the most conspicuous with immune scores; that for ESTIMATE scores were COAD, READ, and bladder urothelial carcinoma (BLCA)." (PMID 34984849, 2022). "Mechanistically, high levels of BCAT1 depleted α-ketoglutarate (α-KG) and promoted expression of SOX2, a transcription factor regulating cancer cell stemness and metastasis." (PMID 34646394, 2021). "Enzymes that catalyze the first step of BCAA degradation, branched-chain aminotransferase 1 (BCAT1) and branched-chain aminotransferase 2 (BCAT2), are commonly upregulated in cancer cells." (PMID 35155562, 2021). "Branched-chain aminotransferase 1/2 (BCAT1/ BCAT1) enzymes, which are involved in BCAA degradation, are proposed to be a prognostic marker for cancer." (PMID 34822435, 2021). "Several other genes, such as BCAT1, BCL2, and ATF6, are related to prognosis in other types of cancers." (PMID 34771630, 2021). "Using the upper IQR values measured in non-neoplastic tissues as positivity thresholds, hypermethylation of BCAT1 and IKZF1 was observed in 82/91 (90.1%) and 75/91 (82.4%) of cancers, respectively, with 86/91 (94.5%) having elevated levels for either marker." (PMID 29796114, 2018). "This study has shown that BCAT1 and IKZF1 methylation are common events in CRC with almost all cancer tissues showing significant levels of methylation in the two genes." (PMID 29796114, 2018). "Of the genes tested in plasma, BCAT1, GRASP, IKZF1, IRF4, SDC2, SEPT9 and SOX21 exhibited high sensitivity (≈55% or greater) for detection of methylated ctDNA in cancer patients." (PMID 27983717, 2016). "Methylated BCAT1 and IKZF1 DNA were detected in respectively 48 (65%) and 50 (68%) of the 74 cancers." (PMID 25928810, 2015).